MYBL2 (MYB proto-oncogene like 2)
Diseases named in the same sentence as MYBL2 in open-access papers (continued):
Sharing a sentence is not in itself a finding about the gene and the disease.
breast cancer (continued). "Since ETS1 and MYBL2 as well as EIF4EBP1 are overexpressed in other cancer entities, for instance in colorectal cancer or breast cancer, these transcription factors might also regulate EIF4EBP1 expression in cancers outside the CNS." (PMID 35228525, 2022). "Similarly, genes MYBL2 and CSE1L with high methylation aberration frequency in breast cancer are both connected to NAE1 with high degree." (PMID 36266635, 2022). "For example, a multigene assay score that is used to predict recurrence in Breast Cancer has a proliferation (tumor growth) component that is composed of the expression of five genes (Ki67, STK15, Survivin, CCNB1, and MYBL2) combined by averaging the five gene scores." (PMID 34657591, 2021). "There were negative expression correlations of hsa-let-7a-5p-CCNB2, hsa-let-7c-5p-CCNB2, hsa-let-7a-5p-AURKB, hsa-miR-30a-5p-CDC20, hsa-miR-30a-5p-MYBL2, hsa-miR-29c-3p-OIP5, hsa-miR-10b-5p-CHAF1B, hsa-miR-195-5p-CCNE1, and hsa-miR-497-5p-CCNE1 in ERα positive breast cancer." (PMID 32500028, 2020). "To conclude, ABRACL could be transcriptionally regulated by MYBL2 to promote cell malignant biological behaviors in breast cancer cells, implying the potential of ABRACL being a promising target for the improvement of breast cancer therapy." (PMID 35341461, 2022). "We performed experiments with cell lines representing various breast cancer subtypes to test our hypothesis that paclitaxel acts synergistically with doxorubicin via suppression of MELK, which in turn attenuates MYBL2 gene expression, known to be advantageous for chemotherapy response." (PMID 24349128, 2013). "Furthermore, MYBL2 overexpression also upregulated the content of ABRACL, suggesting that the high expression of ABRACL might contribute to the malignant biological behaviors and EMT process of breast cancer cells as well." (PMID 35341461, 2022). "In contrast, small interfering RNA (siRNA)-mediated knockdown of MYBL2 downregulated reporter activity in MCF7 and T47D cells as well as the estrogen receptor–negative breast cancer line Hs578T, revealing that B-Myb might modulate A3B promoter activity in breast cancer cells." (PMID 28276478, 2017).
hepatocellular carcinoma (23 papers, 2013 to 2026). A malignant tumor that arises from hepatocytes. "Research has indicated that elevated MYBL2 expression in various tumors is linked to unfavorable prognoses, as observed in bladder cancer and hepatocellular carcinoma." (PMID 38725627, 2024). "Additionally, YAP-dependent induction of UHMK1 has been reported to support the nuclear enrichment of the MYBL2 oncogene, leading to the proliferation of hepatocellular carcinoma cells as demonstrated in YAP-deficient mice and human hepatocellular carcinoma tissues." (PMID 35359403, 2022). "MYBL2 is reported to play a role in many diseases, such as pan-cancer, hepatocellular carcinoma, renal caner." (PMID 40034749, 2025). "The expression levels of MYBL2 were positively correlated with those of E2F1 in hepatocellular carcinomas, and downregulation of E2F1 in hepatocellular carcinoma cells reduced MYBL2 expression." (PMID 39613162, 2024). "Several scientists pointed out that CDC20, CEP55, TRIP13, MYBL2 were overexpressed in hepatocellular carcinoma, compared with adjacent normal tissues." (PMID 38297250, 2024). "A large body of literature has found that MYBL2 overexpression plays an oncogenic role in cancers, such as colorectal cancer and hepatocellular carcinoma." (PMID 35341461, 2022). "All members of the miR‐30 family target MYBL2 in hepatocellular carcinoma and inhibition of MYBL2 expression by miR‐30a in PCa and nonsmall cell lung cancer were reported earlier." (PMID 35612714, 2022). "Univariate and multivariate regression analyses confirmed that high expression level of MYBL2 mRNA was an independent prognostic factor in patients with hepatocellular carcinoma." (PMID 35664780, 2022). "An increasing number of research studies have validated that MYBL2 overexpression plays an oncogenic role in cancers like triple negative breast cancer, colorectal cancer, and hepatocellular carcinoma." (PMID 35341461, 2022). "Additionally, a study by Frau showed that increased expression of MYBL2 in hepatocellular carcinoma actively contributed to the biological progression of tumors by influencing the cell cycle." (PMID 38725627, 2024).
lung cancer (23 papers, 2016 to 2026). A malignant neoplasm involving the lung. "Our previous study that integrated RNA-seq and DNA methylation datasets from lung adenocarcinoma tissues suggested that MYBL2 is a key transcriptional regulator linked to lung cancer." (PMID 36291764, 2022). "Previous studies had implicated FOXM1 and MYBL2 in lung cancer, but our analysis documents their profound effects on gene deregulation, potentially affecting hundreds of enhancers." (PMID 32925947, 2020). "FOXM1 and MYBL2 motifs were enriched at CENPA, FOXM1, and MYBL2-linked enhancers we found in lung cancer cells (91.8% for a FOXM1 motif, 60.3% for an MYBL2 motif)." (PMID 32925947, 2020). "We also utilized two normal lung epithelial cell lines and seven lung cancer cell lines, and found that in lung cancer cell lines, the expression of MYBL2 and RRM2 is higher, which is consistent with the results from clinical samples." (PMID 40885709, 2025). "To validate MYBL2-mediated transcriptional regulation of RRM2 in KRAS G12C mutant lung cancer, we identified two putative MYBL2-binding motifs within the predicted RRM2 promoter region (-2000 to +60)." (PMID 40885709, 2025). "Dual-luciferase reporter assays in lung cancer cell lines (H2122 and H23) demonstrated that MYBL2 overexpression significantly enhanced RRM2 promoter activity." (PMID 40885709, 2025). "MYBL2 (v-myb avian myeloblastosis viral oncogene homolog-like 2) functions as a transcription factor regulating cell progression and is consistently overexpressed in aggressive forms of lung cancer." (PMID 40565055, 2025). "For lung cancer, major pathways included mitotic regulation, metabolic reprogramming, and tight junction integrity, having highly enriched genes such as MYBL2 (driving cell cycle) and FOLR1 (facilitating tumor growth through folate metabolism)." (PMID 40565055, 2025). "To evaluate the clinical significance of MYBL2-RRM2 axis in lung cancer, we first observed that MYBL2 and RRM2 are highly expressed in cancer tissues compared to adjacent normal tissues across multiple cancer types in TCGA." (PMID 40885709, 2025). "High expression of transcription factors FOXM1, MYBL2, and UBE2C was associated with better survival in colon cancer patients, yet showed the opposite effect in stomach and lung cancers, aligning with our findings." (PMID 39542983, 2024). "The importance of FOXM1 and MYBL2 in regulating the biological processes that trigger lung cancer can be seen from the smallest CCP formed when comparing all co-expression networks, to the largest CCP formed among RNA-Seq studies of lung cancer." (PMID 36661515, 2023). "While the average risk for brain metastases for all lung cancers is ~15%, we find that MYBL2 High LUAD patients have a risk of ~40% while MYBL2 Low have a risk of <10%." (PMID 36358918, 2022). "The small coregulatory network has two winning TFs (FOXM1 and MYBL2) coexpressed in the gene networks that coexpressed with the common winning DEGs between the three types of cancer and the winning DEGs related to lung cancer." (PMID 36101460, 2022). "Similarly, in colorectal cancer 71 and lung cancer 72, MYBL2 has been found to promote tumorigenicity." (PMID 38577605, 2024). "For lung cancer, all manuscript-referenced genes were captured by either SHAP or LIME, with notable overlaps such as MYBL2, HYAL1, CLIC5, ADGRF5, and CLDN18." (PMID 40565055, 2025). "All possible comparisons between co-expression networks of lung cancer and PAH have CCPs, which can be regulated by two top deregulated TFs, FOXM1 and MYBL2, according to the iRegulon analysis." (PMID 36661515, 2023). "We also provided insights into how MYBL2, FOXM1, and cell-cycle genes, which are critical for lung cancer patient survival, are regulated in lung adenocarcinoma cells." (PMID 36291764, 2022).
lung cancer (continued). "FOXM1 is overregulated in nine lung cancer datasets and is related to: 1) the negative regulation of transcription along with E2F1, FOXE1, and HMGA1; 2) cellular senescence along with E2F1, E2F3, and MYBL2; and 3) DNA repair and damage." (PMID 39228892, 2024). "Moreover, FOXM1 is co-expressed in the CCPs of LC microarray datasets, and PAH, FOXM1, and MYBL2 are co-expressed in the CCP of all LC microarray datasets, suggesting their key importance during the lung cancer oncogenic process." (PMID 36661515, 2023). "However, MYBL2 is only co-expressed in lung cancer microarray CCP, TBX4 is only co-expressed in lung cancer RNA-Seq CCP, PKNOX2 is not co-expressed in any CCP, and neither is a regulator in the GRNs." (PMID 36661515, 2023).
lung adenocarcinoma (22 papers, 2018 to 2025). A carcinoma that arises from the lung and is characterized by the presence of malignant glandular epithelial cells. "The upregulation of MYBL2 as a key MAG in lung adenocarcinomas was associated with low response to erlotinib." (PMID 38835346, 2024). "Previously, we and other research groups have studied genes that contribute to lung adenocarcinoma progression and found that overexpression of MYBL2 (alias B-MYB) is associated with poor survival of lung adenocarcinoma patients." (PMID 36291764, 2022). "Overexpression of MYBL2 is associated with poor survival of lung adenocarcinoma patients, but the molecular mechanism by which it regulates transcription and carcinogenesis has not yet been elucidated." (PMID 36291764, 2022). "Previously, we showed that transcription factor MYBL2 expression is associated with the survival of lung adenocarcinoma patients." (PMID 36291764, 2022). "Analysis of genomic sequencing data demonstrated that MYBL2 High lung adenocarcinomas had elevated somatic mutation burden, widespread chromosomal alterations, and alterations in single-strand DNA break repair pathways." (PMID 33489883, 2020). "Analysis of omics data revealed that MYBL2 High lung adenocarcinomas had significantly elevated somatic mutations and widespread chromosomal alterations characteristic of genomic instability." (PMID 33489883, 2020). "High expression of CENPA, FOXM1, and MYBL2 is particularly observed in a subgroup of lung adenocarcinomas and is associated with poor patient survival." (PMID 32925947, 2020). "In addition, MYBL2 belongs to the five key microtubule-associated genes (MAGs) in lung adenocarcinomas." (PMID 38835346, 2024). "MYBL2 is reported to be associated with the prognosis of lung adenocarcinoma." (PMID 36291764, 2022). "Moreover, overexpression of MYBL2 is associated with poor survival of lung adenocarcinoma patients." (PMID 36291764, 2022). "Clinical staging revealed a positive correlation between higher stages of lung adenocarcinoma and increased staining intensity of MYBL2 and RRM2." (PMID 40885709, 2025). "All showed a very strong correlation between MYBL2 and RRM2, indicating that MYBL2 probably functions as a transcription factor of RRM2 in lung adenocarcinoma." (PMID 40885709, 2025). "We employed a tissue microarray (TMA) containing 78 lung adenocarcinoma samples with complete clinical information and performed immunohistochemical (IHC) staining of MYBL2 and RRM2." (PMID 40885709, 2025). "The findings demonstrated that high expression levels of MYBL2 and RRM2 were associated with shorter survival times in lung adenocarcinoma patients." (PMID 40885709, 2025). "Previous research showed that MYBL2 was upregulated by lung adenocarcinoma tumors to serve as an important driver of error-prone DNA repair, indicating an important role for this gene in facilitating the progression of other cancers." (PMID 37509213, 2023). "It has been reported that the expression of UBE2C and MYBL2 was significantly positively correlated in a variety of cancers (including lung adenocarcinoma, lung squamous cell carcinoma, etc.)except GC." (PMID 37840753, 2023). "miR-30c-2-3p promotes the development of lung adenocarcinoma by targeting MYBL2 and regulating CELL CYCLE Signaling Pathway." (PMID 36147493, 2022). "Lastly, we assessed potential treatment options for the disease by treating lung adenocarcinoma cells with an inhibitor targeting MYBL2 and FOXM1." (PMID 36291764, 2022). "In this study, we performed ChIP-seq using an MYBL2-targeted antibody and discovered that MYBL2 primarily binds to the promoters of highly expressed genes in lung adenocarcinoma cells." (PMID 36291764, 2022). "In this study, we mapped the global binding sites of MYBL2 and found that MYBL2 binds to the promoters of genes that are highly expressed in lung adenocarcinoma." (PMID 36291764, 2022).
lung adenocarcinoma (continued). "Previous work from our group revealed that elevated expression of the transcription factor MYB proto-oncogene like 2 (MYBL2) identified lung adenocarcinomas with genomic instability and wildtype BRCA." (PMID 36358918, 2022). "This indicates that treatment with FDI-6 can reduce the activities of FOXM1 as well as MYBL2 in nuclei of the lung adenocarcinoma cells." (PMID 36291764, 2022). "We also found that cyclin B1 (CCNB1) is regulated by MYBL2 and FOXM1, and overexpression of CCNB1 is associated with poor survival of lung adenocarcinoma patients." (PMID 36291764, 2022). "We profiled the transcriptome upon MYBL2 knockdown to identify genes regulated by MYBL2 in lung adenocarcinoma cells." (PMID 36291764, 2022). "This suggests that MYBL2 is a crucial transcription factor that regulates oncogenes in lung adenocarcinoma." (PMID 36291764, 2022). "In conclusion, it is suggested that FDI-6 can change the expression of genes involved in cell cycle regulation, affecting the activity of both FOXM1 and MYBL2 in lung adenocarcinoma cells." (PMID 36291764, 2022). "We performed ChIP-seq (chromatin immunoprecipitation coupled with sequencing) to identify binding sites of MYBL2 in lung adenocarcinoma cells." (PMID 36291764, 2022). "In this study, we characterized the functions of MYBL2 in lung adenocarcinoma cells by generating global binding profiles of MYBL2 and transcriptome profiles upon knockdown experiments." (PMID 36291764, 2022). "We discovered that MYBL2 regulates cell cycle genes by binding to the promoters of highly expressed genes in lung adenocarcinoma cells working with FOXM1." (PMID 36291764, 2022). "This additive effect upon knockdown of both FOXM1 and MYBL2 suggests that these factors work together as transcriptional activators in lung adenocarcinoma cells." (PMID 36291764, 2022). "We identified individual lung adenocarcinoma enhancers linked to CENPA, FOXM1, or MYBL2 that were associated with poor patient survival." (PMID 32925947, 2020). "Subsequent Kaplan-Meier analyses revealed that patients with MYBL2 High lung adenocarcinomas had significantly worse OS rates, compared to patients with MYBL2 Low lung adenocarcinomas (ΔMMS = 49.6 months, log-rank p = 2.2e–3)." (PMID 33489883, 2020). "We found that MYBL2 High lung adenocarcinomas significantly overexpressed DNA repair proteins that support replication fork stability and MMEJ repair." (PMID 33489883, 2020). "Collectively, our study highlights the importance of MYBL2 in coordinating replication stress responses and error-prone repair in lung adenocarcinomas with proficient HR pathways." (PMID 33489883, 2020). "Our study supports the use of checkpoint kinase 1 (CHK1) pharmacological inhibitors, in targeted MYBL2 High patient cohorts, as a future therapy to improve lung adenocarcinoma patient outcomes." (PMID 33489883, 2020). "Collectively, our data supports the use of prexasertib, an effective CHK1 inhibitor, for targeting MYBL2 High lung adenocarcinoma cells displaying widespread replication stress and ineffective HR repair." (PMID 33489883, 2020). "Across two independent studies, elevated MYBL2 expression identified lung adenocarcinoma patients with significantly poorer OS and DFS outcomes, early onset disease, increased regional lymph node involvement, and increased prevalence of distant metastases." (PMID 33489883, 2020). "TCGA lung adenocarcinomas were stratified into MYBL2 High and MYBL2 Low cohorts using a modified quartile-based method." (PMID 33489883, 2020). "In this study, we provide evidence that lung adenocarcinomas displaying ineffective HR overexpress the DNA-damage responsive transcription factor MYB proto-oncogene like 2 (MYBL2) (MYBL2 High)." (PMID 33489883, 2020).